BRCA1 (BRCA1 DNA repair associated)
Diseases named in the same sentence as BRCA1 in open-access papers (continued):
Sharing a sentence is not in itself a finding about the gene and the disease.
breast cancer (continued). "Heterozygous BRCA1 mutations increase the risk of breast cancer but can also cause neuronal migration defects." (PMID 33441416, 2021). "A number of systematic reviews addressing breast cancer risk associated with HRT following RRBSO in BRCA1/2 mutation carriers have been published." (PMID 33885953, 2021). "While FDA guidelines indicate olaparib (AZD2281) and talazoparib for HER2-negative disease, the panel supports their use in any breast cancer subtype associated with germline BRCA1 or BRCA2 mutations 8,9 (NCCN guideline Ver." (PMID 33767581, 2021). "We classified our data into BRCA positive and BRCA negative groups for identifying the association of ATM variants with BRCA1/2 mutation in breast cancer patients." (PMID 34493284, 2021). "Among 3950 breast cancer patients who were tested for BRCA1/2 mutation between January 2008 and November 2019 in Samsung Medical Center, 486 patients were BRCA1/2 mutation carriers." (PMID 34285295, 2021). "Genetic predisposition accounts for 10–30% of breast cancer cases, and its rate of finding germline pathogenic variants in BRCA1 or BRCA2 (gBRCA) was 3–5%." (PMID 33649982, 2021). "Women with an inherited BRCA1 mutation have a lifetime risk of developing breast cancer of approximately 70%." (PMID 34283078, 2021). "While PARPi therapy has been successfully employed as monotherapy for BRCA1-deficient ovarian tumors, there is less evidence supporting such a response in BRCA1-deficient breast cancer." (PMID 34070674, 2021). "Another study indicathat ATM mutations and BRCA1 mutations are associated with breast cancer patients." (PMID 34493284, 2021). "PIK3CA is the third most mutated gene in basal-like breast cancer, followed by retinoblastoma (RB) and BRCA1/2." (PMID 33435254, 2021). "Multiple studies have demonstrated the estimated lifetime breast cancer risk for BRCA1 carriers to be about 80% and 70% for BRCA2 carriers." (PMID 34573353, 2021). "Similar effects of TGFβ and cisplatin on morphological changes, gene expression, and migration of a murine cell line, 69 that was derived from a mouse Brca1 deficient mammary tumor 38, was observed." (PMID 33500735, 2021). "Mutations in the BRCA1/2 genes identified in breast cancer and ovarian cancer patients by Sanger and next generation sequencing technologies." (PMID 34490083, 2021). "Gao and colleagues found RASSF1A function-depleting single-nucleotide polymorphisms A133S in BRCA1/2 gene mutation carriers with early-onset breast cancer." (PMID 34209669, 2021). "For BRCA1 heterozygotes the ER-negative PRS313 showed the largest association with all contralateral breast cancer, HR per SD = 1.12, 95% CI (1.06–1.18), p value = 6.0×10−5, C-index 0.53, 95% CI (0.51–0.55)." (PMID 34113011, 2021). "Breast cancer is the leading cancer diagnosis among US women, and is a useful comparator for PCa because both can be inherited, and genetic mutations in BRCA1/2 also affect screening and treatment recommendations in breast cancer." (PMID 34542414, 2021). "Patients with a germline mutation in the breast cancer susceptibility genes Breast cancer 1 (BRCA1) or Breast cancer 2 (BRCA2) have a high risk of developing breast cancer or ovarian cancer and show high sensitivity to these DNA damaging agents." (PMID 33670893, 2021). "Hereditary breast and ovarian cancer (HBOC) risk has been traditionally linked to germline pathogenic variants (PVs) in breast cancer 1 and 2 genes (BRCA1 and BRCA2)." (PMID 33498765, 2021). "In this context, this study is an attempt to elucidate the long-term prognostic implications of BRCA1/2 mutations in Egyptian female breast cancer patients over 24 years." (PMID 34206661, 2021). "Similar to osteosarcoma, malignant canine mammary tumors and human breast cancer share similar epidemiology and disease behavior showing breaking point cluster region 1 (BRCA1) mutations and susceptibility to steroid hormones." (PMID 33544704, 2021).
breast cancer (continued). "Age, mutations in Breast Cancer Gene 1 or 2 (BRCA1 or BRCA2) genes, and dense breast tissue are the highest risk factors." (PMID 34638847, 2021). "This review aimed to provide significant insights into up-to-date knowledge about the role of BRCA1/2-mutated tumor microenvironment and possible mechanisms by which it interacts with and promotes breast cancer development and progression." (PMID 33540843, 2021). "For example, the increased probability of having breast cancer given a mutated BRCA1 gene in conjunction with a particular patient having a mutated BRCA1 gene explains the patient having breast cancer." (PMID 34966640, 2021). "The pathogenic variant c.815_824dup of BRCA1 has been reported as the most frequent among African American populations with inherited breast cancer and was supposed to have a West African origin." (PMID 35096615, 2021). "In particular, for breast cancer, BRCA1 associates with EZH2 in a binding region that overlaps with a HOTAIR-binding domain, thus blocking HOTAIR–EZH2 (PRC2) interaction." (PMID 34073224, 2021). "Mutational signature 3 is a genomic feature associated with failure of DNA DSB repair in breast cancer and is highly related to BRCA1/2 variation." (PMID 34465315, 2021). "A beneficial effect of oophorectomy on breast-cancer survival has been seen in BRCA1 mutation carriers with hazard ratios ranging from 0.4 to 0.6." (PMID 33597716, 2021). "For example, pathogenic variants in BRCA1 conferred the highest breast cancer risk in the triple negative subgroup than that in other subgroups." (PMID 34606182, 2021). "Estimates show that 5–10% of breast cancer cases are hereditary, caused by genetic variants in autosomal dominant genes; of these, 16% are due to germline mutations in the BRCA1 and BRCA2 genes." (PMID 33499154, 2021). "The European Society of Breast Cancer Specialists (EUSOMA) mentions that approximately 3% of all breast cancers occur in women with BRCA1 and BRCA2 deleterious mutations." (PMID 33859904, 2021). "There is also the option of maintenance treatment with olaparib in patients with germline mutations of breast cancer gene 1 or 2 (BRCA1 or 2) who have responded to cancer treatment, as demonstrated by the POLO trial." (PMID 34925974, 2021). "Although not statistically significant, we observed a higher risk of developing contralateral breast cancer for BRCA1/2 mutation carriers who underwent ipsilateral surgery-only compared to those who underwent contralateral RRM." (PMID 34285295, 2021). "In breast cancer, the germlines BRCA1, BRCA2, as well as somatic BRCA1 were associated with DNA damage/repair, cell cycle, chromosome maintenance, and transcription." (PMID 33525353, 2021). "This impairment of dsDNA break repair is similar to that which occurs in breast cancer pathogenesis in patients with BRCA1/2 mutations." (PMID 34070674, 2021). "THRs have been identified to be highly expressed in breast cancer tissue deriving from patients diagnosed with a BRCA1 germline mutation." (PMID 33478016, 2021). "Breast cancer and ovarian cancer are both associated with mutations and/or overexpression/amplification in certain genes (e.g. BRCA1, BRCA2, PIK3C, ERBB2, etc.)and aberrations in related pathways, which exhibits a risk of co-occurrence in women." (PMID 34181736, 2021). "Taken together, these results manifested that the BRCA1-deficient mammary tumors bear great intertumor heterogeneity." (PMID 34815798, 2021). "TR expression was associated with higher 5-year survival in metastasized BRCA1 mutated breast cancer." (PMID 34315420, 2021). "The cumulative lifetime risk of breast cancer that is conferred by pathogenic BRCA1 and BRCA2 variants is estimated to be 65–79% and 61–77%, respectively." (PMID 34771713, 2021). "BRCA1-associated breast cancers have aggressive pathological traits and are mainly hormone receptor-negative, whereas BRCA2-associated breast cancers have sporadic characteristics and are predominantly hormone receptor-positive." (PMID 34828379, 2021).
breast cancer (continued). "This is in contrast to cells derived from true basal phenotypic cells as is the case in heritable BRCA1-mutated breast cancers." (PMID 34912374, 2021). "In women with breast cancer, the prevalence of pathogenic BRCA1/BRCA2 variants is approximately 1 in 33, and almost 1 in 8 if the affected individual is an AYA." (PMID 34771713, 2021). "The majority (approximately 80%) of breast cancers arising in BRCA1 germline mutation are TNBC, while 11–16% of all TNBC harbor BRCA1 or BRCA2 germline mutations." (PMID 34503097, 2021). "Nevertheless, within the cohort of young BRCA-mutated breast cancer patients, the prognostic implications of carrying a germline BRCA1 or BRCA2 pathogenic variant as well as potential differences according to hormone receptor status remained largely undefined." (PMID 33579978, 2021). "Breast cancer patients with pathogenic mutations (such as BRCA1/2, CHECK, PALB and ATM) are more prone to have false negative axillary US examinations compared to high-risk breast cancer patients without genetic changes." (PMID 34945851, 2021). "Studies have shown that the use of tamoxifen was associated with an approximately 45%–60% reduction in the risk of contralateral breast cancer in affected women with BRCA1 and 2 mutations." (PMID 33996049, 2021). "It is estimated that 5% to 10% of breast cancer cases are related to inherited predisposition genes, with germline BRCA1 and BRCA2 pathogenic variants (BRCA PV) being the most common." (PMID 35875314, 2021). "Tumor cells that are defective in either of the breast cancer susceptibility genes (i.e., BRCA1 or BRCA2) are sensitive to the inhibition of PARP1." (PMID 34359565, 2021). "We also show that among breast cancer patients who have germline BRCA1/2 mutations, if their tumors also show high cyclin E RNA or high levels of LMWE protein expression, they have worse clinical outcomes." (PMID 33916118, 2021). "Herein, we show that radiotherapy is a viable approach for proactively treating the progression of BRCA1-associated breast cancer." (PMID 33767581, 2021). "While the clinicopathological characterization of germline BRCA1 mutated breast cancer has been well defined, there is still little known in regards to the pathological signature of BRCA1 gene hypermethylated breast cancer in women." (PMID 33808555, 2021). "In conclusion, TNBC is associated with BRCA1/2 at a higher rate than the rest of the breast cancer types and targeted therapy treatment needs to be frequently tailored according to the patient." (PMID 34072659, 2021). "This review aims to provide significant insights into up-to-date knowledge about the role of BRCA1/2-mutated tumor microenvironment and possible mechanisms by which it interacts with and promotes breast cancer development and progression." (PMID 33540843, 2021). "According to recent prospective data, the cumulative risk at the age of 80 years in BRCA1 mutation carriers is up to 72% for breast cancer and up to 44% for ovarian cancer." (PMID 33885953, 2021). "An essential role in regulating microtubule nucleation in breast cancer is played by γ-tubulin ubiquitylation by the BRCA1 (breast cancer type 1 susceptibility protein)/BARD1 (BRCA1-associated RING domain protein 1) E3 ligase complex." (PMID 34830792, 2021). "The phase III BROCADE3 trial compared veliparib plus carboplatin plus paclitaxel versus placebo combined with carboplatin and paclitaxel in patients with HER2-negative advanced breast cancer and a germline BRCA1 or BRCA2 mutation (NCT02163694)." (PMID 33802424, 2021). "Most of the individuals were breast cancer patients, being BRCA1 mutations responsible for 50% of the pathogenic variants in these patients." (PMID 33827469, 2021).
breast cancer (continued). "Studies reported a positive correlation between TILs, PD-L1 expression on ovarian cancer cells, and the presence of breast cancer genes 1 and 2 (BRCA1 and 2) mutations." (PMID 34946254, 2021). "The cumulative incidence of breast cancer at the age of 70 years in men is 1% for BRCA1 mutation and 7% in BRCA2 mutation." (PMID 33996049, 2021). "The majority of breast cancers in patients who carry a germline BRCA1 variant are the basal subtype of triple negative breast cancer (TNBC)." (PMID 34771713, 2021). "CPI is proposed as an alternative to UBC patients harboring BRCA1/2 mutations who underwent standard loco-regional treatment for the primary breast cancer and declined CRRM." (PMID 34563200, 2021). "In fact, about 5% of all breast cancers bear a BRCA1/2 germline pathogenic variant (PV), being a tissue sensitive to PARP inhibitors, and thus treatment with this type of molecule is feasible." (PMID 34072659, 2021). "Currently, germline or somatic mutations in BRCA1/2 genes are investigated in clinical practice for risk assessment, diagnosis, and treatment decision-making in breast cancer patients." (PMID 34281208, 2021). "BRCA1/2 pathogenic variants account for approximately 1–2% of all breast cancer cases and the prevalence of BRCA1/2 pathogenic variants in the general population is about 1 in 400 individuals." (PMID 33507482, 2021). "In accordance with this, a large-scale analysis in 1269 breast cancer patients revealed that low protein expression of BRCA1 was associated with high numbers of CD8+ TILs as compared to patients with normal BRCA1 expression." (PMID 34067105, 2021). "There are other high penetrance gene mutations associated with breast cancer, but BRCA1 and BRCA2 are best elucidated." (PMID 33996049, 2021). "The loss of the BRCA1 protein, as occurs in many breast cancers, induces centrosome amplification and enhances the formation of large microtubule asters from centrosomes." (PMID 34830792, 2021). "BRCA1/2 mutations play a significant role in determining clinical prognosis and survival curves in breast cancer patients." (PMID 34070674, 2021). "Our data and those of Kowalik indicate that pathogenic BRCA1/2 variants are more common in TNBC than in other types of breast cancer." (PMID 33918338, 2021). "These genes are highly penetrant; there is a reported cumulative risk of almost 80% for female breast cancers in BRCA1 mutations, as well as a 50% risk for BRCA2 mutation carriers." (PMID 33582622, 2021). "A recent study has also reported that germline BRCA1 mutations in breast cancer patients appear to be associated with an increased risk of brain metastasis even when accounting for other confounding factors, such as age and stage." (PMID 35008272, 2021). "Several PARPi have been approved for the treatment of BRCA1/2- mutated ovarian and breast cancers, and have now been also approved for prostate and pancreatic cancers." (PMID 34503215, 2021). "In humans, germline heterozygous BRCA1 mutations cause the highest risk and earliest onset of breast cancer, followed by BRCA2 and then PALB2 mutations." (PMID 33893322, 2021). "Prophylactic bilateral mastectomy reduces breast cancer mortality and morbidity in higher familial risk women, particularly those with BRCA1/2 genetic mutations." (PMID 32524330, 2021). "The current study provides insights into the potential mechanisms by which excess body fat increases breast cancer penetrance in women with BRCA1 or BRCA2 mutations, including in pre-menopausal women." (PMID 33649363, 2021). "Among families with three or more affected men, risk measured for the sentinel pair had effect sizes analogous to those known for breast cancer predisposition by pathogenic variants of BRCA1 and BRCA238." (PMID 34059701, 2021). "In Jamaica, we found a 5.5% (10 of 183) rate of inherited breast cancer with germline variants in BRCA1, BRCA2, PALB2, STK11, and NBN genes." (PMID 33646313, 2021).
breast cancer (continued). "The mutual exclusivity of BRF2 amplification and BRCA1/2 loss was also observed in breast cancer cell lines in the CCLE database." (PMID 34359683, 2021). "Data for the Chinese population showed that the pathogenic or likely pathogenic mutations of BRCA1/2 were identified in 5.3% unselected Chinese breast cancer patients and in 18.1% familial breast cancer patients." (PMID 34917121, 2021). "As the BRCA1 and BRCA2 gene products are involved in homologous recombination, the identification of BRCA1/2-deficient tumors in breast cancer patient implied important treatment connotations." (PMID 33540843, 2021). "Preclinical data also suggest a favorable activity of Pt agents in TNBC and BRCA1-associated breast cancer." (PMID 34938186, 2021). "The occurrence of compound heterozygous mutations of BRCA1 gene is very rare among breast cancer patients." (PMID 33477375, 2021). "Integrating these genomic features into a score termed HRDetect demonstrates a very high sensitivity for HRRd associated with BRCA1/2 loss in breast cancers." (PMID 34877933, 2021). "BRCA1/2 mutations occur in 3-4% of all patients with breast cancer and in 10% of those with triple negative breast cancer." (PMID 34422626, 2021). "Although there is extensive literature suggesting that estrogens play a role in the pathogenesis of breast cancer in BRCA1/2 mutation carriers, this study investigated the relationship between BMI and breast aromatase expression." (PMID 33649363, 2021). "PARP inhibitors have been established as important new therapies for breast cancer patients with inherited BRCA1/2 mutations." (PMID 34839359, 2021). "De novo somatic BRCA1/2 mutations in breast cancer are considered to be rare: the prevalence of somatic BRCA1 gene mutations in primary tumors is only 1.55%, and that of somatic BRCA2 gene mutations is 1.68%42." (PMID 33854152, 2021). "The notably high frequency of BRCA1 mutations found in the present PABC group (30%) places pregnant breast cancer patients in a high-risk setting." (PMID 34011307, 2021). "The penetrance or cumulative lifetime risk of developing breast cancer is estimated at 72% for BRCA1 and 69% for BRCA2 pathogenic variant carriers." (PMID 34072979, 2021). "Individuals carrying mutations in BRCA1/BRCA are associated with a higher lifetime risk of up to 60–85% for breast cancer, and 17–39% for ovarian cancer by the age of 70." (PMID 34525964, 2021). "Even though inherited genetic factors such as BRCA1/2 mutations result in 5-10% of cases of breast cancer, lifestyle is now considered as an increasingly contributing factor to the etiology of breast cancer." (PMID 34212054, 2021). "In 15–20% of EOC patients, there is a mutation in the tumor suppressor genes breast cancer 1/2 (BRCA1/2), leading to a familial accumulation of ovarian and breast cancer." (PMID 34206491, 2021). "Lastly, the third step included laboratory in vivo research on the clinical, molecular, and pathologic features CSCs breast cancer in BRCA1 and BRCA2 mutations." (PMID 34377198, 2021). "Recently, olaparib, a polyADP-ribose polymerase (PARP) inhibitor, was approved by the US Food and Drug Administration for the treatment of breast cancers with BRCA1/2 mutations." (PMID 33628586, 2021). "The cumulative risk 20 years after breast cancer diagnosis was estimated to be 40% for BRCA1 carriers and about 26% for BRCA2 carriers." (PMID 34490083, 2021). "Other examples of biomarkers excluded in this review are the loss of tumor suppressors in cancer such as breast cancer genes 1 and 2 (BRCA-1, BRCA-2), RNAs, proteins such as prostate-specific antigen (PSA) or circulating tumor DNA (ct-DNA)." (PMID 34208595, 2021). "The best known and most penetrant germline genetic mutations responsible for ovarian cancer are in the tumor suppressor breast cancer susceptibility genes 1 and 2 (BRCA1 and BRCA2), which are noted in 13–20% of ovarian cancers." (PMID 33419231, 2021).